MRPS33 (mitochondrial ribosomal protein S33)
Synonyms: MRP-S33; S33mt; CGI-139; PTD003; mS33
Tractability: Small molecule: a structure with a bound ligand is known. PROTAC: its protein half-life has been measured.
Gene: Protein-coding gene on chromosome 7 (141,002,610 to 141,015,228, reverse strand). Ensembl gene ENSG00000090263.
Subcellular location: Mitochondrion
Pathways (Reactome):
Metabolism of proteins: Mitochondrial ribosome-associated quality control; Mitochondrial translation elongation; Mitochondrial translation initiation; Mitochondrial translation termination
Gene Ontology:
Molecular function: structural constituent of ribosome
Biological process: mitochondrial translation; translation
Cellular component: mitochondrion; mitochondrial inner membrane; mitochondrial small ribosomal subunit
Genetic constraint (gnomAD): Loss-of-function variants: 11 observed, 11.52 expected, observed/expected ratio (o/e) 0.95, 90% interval 0.6 to 1.57. The upper end of that interval is the gene's LOEUF score, 1.57, which puts it in group 6 of 6, group 1 being the genes least tolerant of losing a copy. Missense variants: 109 observed, 132.2 expected, observed/expected ratio (o/e) 0.82, 90% interval 0.7 to 0.97. Synonymous variants: 46 observed, 46.17 expected, observed/expected ratio (o/e) 1, 90% interval 0.79 to 1.27.
Homologues: Orthologues: chimpanzee MRPS33 (100% identical), macaque MRPS33 (95% identical), pig MRPS33 (86% identical), guinea pig MRPS33 (85% identical), dog MRPS33 (84% identical), rat Mrps33 (83% identical), mouse Mrps33 (82% identical), zebrafish mrps33 (62% identical), Drosophila melanogaster mRpS33 (59% identical), Caenorhabditis elegans mrps-33 (43% identical).
Diseases named in the same sentence as MRPS33 in open-access papers:
MRPS33 is named in the same sentence as 6 diseases in open-access papers, as found by Europe PMC text mining. Sharing a sentence is not in itself a finding about the gene and the disease. The quoted sentences say what the papers report.
cardiomyopathy (1 paper, 2024). A disease of the heart muscle or myocardium proper. "This study also shows that disruption of the mitochondrial MRPS33 induces severe cardiomyopathy." (PMID 38542224, 2024).
diabetic retinopathy (1 paper, 2025). "This study advances our understanding of diabetic retinopathy pathogenesis by identifying novel genetic variants (ABCA4_rs17110929, MMP2-AS1_rs2576531, FOXP1_rs557869288) and additional loci (MRPS33_rs1533933, DRD2_rs4936270)." (PMID 41010507, 2025).
schizophrenia (1 paper, 2025). A major psychotic disorder characterized by abnormalities in the perception or expression of reality. "Interestingly, MRPS33 has previously been associated with schizophrenia." (PMID 39857704, 2025).
MRPS33 also shares sentences with these, for which no sentence is quoted: Q fever (1 paper); rectal cancer (1); sarcoma (1).